FASN (fatty acid synthase)
Diseases named in the same sentence as FASN in open-access papers (continued):
Sharing a sentence is not in itself a finding about the gene and the disease.
tumor (continued). "Studies have shown that FASN is a particularly informative prognostic predictor in BC; expression was found to be positively correlated with tumor aggressiveness, histologic grade, recurrence, and poor survivability in patient cohorts 34,35." (PMID 32792852, 2020). "Synthetic derivatives of cerulenin, such as the competitive irreversible FASN inhibitor C75 (α-methylene-β-butyrolactone), have been developed, and they display anti-tumor activity in preclinical models." (PMID 33083663, 2020). "The relative expression of FASN mRNA was higher in the tumor tissue in all public databases and our sequencing data (p < 0.001)." (PMID 32655718, 2020). "Unsaturated fat synthase (FASN) down regulation induces apoptosis and represses tumor progression and metastasis." (PMID 32795296, 2020). "To clarify differential FASN mRNA expression in ccRCC, we examined differential FASN expression between tumor and normal paracancerous tissues and identified prognostic value in 913 ccRCC patients of TCGA and FUSCC cohorts." (PMID 33569391, 2020). "More importantly, FASN is involved in the process of lipid metabolism and highly expressed in tumor cells." (PMID 33569391, 2020). "Using Gene Set Enrichment Analysis, FASN activity inhibition is shown to induce widespread changes in tumor metabolism in which FASN inactivation downregulates glycolysis/gluconeogenesis and the Krebs cycle pathway." (PMID 32872164, 2020). "Compared with normal cells, all esterified fatty acids in most tumor cells are synthesized de novo, and expression of FASN in tumor cells is significantly increased, which leads to aggressiveness and a poor prognosis." (PMID 33569391, 2020). "Immunohistochemistry (IHC) staining was performed to validate differential expression levels between tumor and normal samples, which suggested a significantly elevated FASN staining density and intensity in ccRCC tissues compared with those in normal tissues." (PMID 33569391, 2020). "Fatty acid synthase (FASN), a key metabolic enzyme for fatty acid synthesis, can directly promote tumor proliferation and metastasis." (PMID 33117713, 2020). "Consistent with protein data, the level of FASN mRNA is significantly higher in tumor tissues as compared to normal mucosa." (PMID 32850342, 2020). "SK-BR-3 is a representative of HER2 overexpressing tumor subtype that is known to have increased FASN activity resulting in increased lipid synthesis and changes in the lipidome." (PMID 32287294, 2020). "Endogenous FA biogenesis is tandemly activated by ACC and fatty acid synthase (FASN), which constitutes a metastatic stimulus that drives tumor progression." (PMID 32839493, 2020). "Immunoreactivity for FASN mainly localized to the tumor cells and was usually homogeneously distributed throughout the tumor tissue." (PMID 32178271, 2020). "The schema points out that gefitinib-untargetable palmitoylated EGFR impinges on FASN, promoting tumor growth via the AKT pathway." (PMID 32516941, 2020). "As ACLY, ACC, and FASN are frequently upregulated in tumor cells and their inhibition reduces tumor growth, it is widely recognized that the increased capacity for producing lipids de novo is a crucial determinant for the tumor progression." (PMID 32266157, 2020). "FASN expression is up-regulated in many types of cancer, and is closely related to tumor invasiveness and a poor prognosis." (PMID 33585187, 2020). "Increased expression or abnormal activity of key lipogenic enzymes such as fatty acid synthase (FASN) and acetyl coenzyme A (acetyl-CoA) carboxylase is often attributed to the high growth rate and lipogenic phenotype of tumor cells." (PMID 33123488, 2020). "Recently, some scholars have found that the abnormal activation of FASN can blunt the anti-tumor immunity of host." (PMID 33194756, 2020). "In contrast, increased FASN expression promoted PCa cells to resist apoptosis as the tumor progressed to androgen independence, which rendered the gene a metabolic oncogene." (PMID 32655718, 2020).
tumor (continued). "In the majority of studies, the overexpression of FA synthesis enzymes such as ACC, along with its immediate downstream group of enzymes known as FASN, indicates tumor progression and cell malignancy." (PMID 33050166, 2020). "Compared with healthy tissues that prefer to use circulating lipids, tumor cells express a significant amount of FASN protein." (PMID 33330490, 2020). "Normal cells derive FAs exogenously while tumor cells derive FAs both exogenously and by de novo synthesis through FASN." (PMID 32872164, 2020). "Our data in high glucose conditions, which we also previously reported, suggested that IGF-I circumvents tumour suppressive functions of BRCA1 by reducing its association with phosphorylated ACCA and upregulating FASN downstream of ACCA." (PMID 33212987, 2020). "Since the discovery of FASN, its role in tumor growth and intracellular signal transmission has been extensively studied." (PMID 33096860, 2020). "It has been observed that there were significant correlations between FASN expression, tumor size, grade, recurrence, and stage." (PMID 32795296, 2020). "In our previously published study we showed that FASN is significantly overexpressed in primary tumor tissues as compared to matched normal colon mucosa using tissue microarray analysis (TMA)." (PMID 32850342, 2020). "In preclinical models of TNBC tumors, FASN inhibitors in combination with anti-EGFR signaling agents show significant anti-tumor effects in TNBC tumors." (PMID 32296646, 2020). "In vivo treatment with a FASN inhibitor restored the anti-tumor activity of tamoxifen and fulvestrant against fast-growing, hormone-resistant MCF-7/HRG xenograft tumors in mice." (PMID 33081219, 2020). "Our study showed that the panel of ACOT8/ACSL5/FASN/HMGBCS2/SCD1 genes had a better prognostic performance than validated clinical risk scales and is applicable for early detection of CRC and tumor recurrence." (PMID 32155177, 2020). "In intracranial xenograft models, inhibition of FASN by using C75 or shRNA inhibited tumor growth and prolonged survival." (PMID 32178271, 2020). "The advantage of our study is that we first assessed the expression level of FASN mRNA in ccRCC tumor and para-cancerous tissues in two cohorts." (PMID 33569391, 2020). "In OC cell lines, overexpression of FASN has also been observed to promote tumor cell growth and its inhibition serves as a promising therapeutic strategy." (PMID 31932581, 2020). "Among the 147 SDC tumor specimens, ADP and FASN were expressed in at least a limited part of the tumor in 146 cases (both in 99.3%)." (PMID 32103349, 2020). "In the TCGA database, we found that the relative expression of FASN mRNA was significantly higher in tumor tissue compared to benign tissue (p < 0.001)." (PMID 32655718, 2020). "GNPAT acetylation can inhibit TRIM21-mediated FASN degradation and promote lipid synthesis and tumor metabolism." (PMID 33585187, 2020). "SREBP1, along with its target genes (ACC, FASN), is overexpressed in human multiform glioblastoma (EGFR mutated), and both genetic and pharmacological inhibition significantly block tumor-derived xenograft growth." (PMID 33050166, 2020). "Despite the conclusive evidence for FASN involvement in tumor metabolic reprogramming, the clinical scenario has remained uncompleted regarding first generation inhibitors, although it is improving with next-generation FASN inhibitors." (PMID 33050166, 2020). "Fatty acid synthase (FASN), the key enzyme that controls the biosynthesis of fatty acids and lipids, for example, is overexpressed in most tumours and correlates with malignant progression." (PMID 32913236, 2020). "Although the specific mechanism, of how lncRNAs regulate lipid synthesis involving FASN is unclear, they at least partly demonstrate that lncRNAs play an important role in tumor cells by FASN-mediated lipid synthesis." (PMID 31850189, 2019).
tumor (continued). "For instance, the drug orlistat that was used in this study, was discovered to have anti-tumor activity through FASN inhibition as a beneficial side effect, next to its known activity as lipase inhibitor." (PMID 30682837, 2019). "A 0–2, 2–4, 4–6-fold induction in FASN expression was observed in 14, 12 and 6 tumor sections, respectively." (PMID 30717356, 2019). "The SCD inhibitor BZ36 and FASN inhibitor C75 have shown anti-tumor effects in a pre-clinical xenograft model." (PMID 31083642, 2019). "Recent studies have provided evidence that several key proteins in metabolic reprogramming, including PKM2 and FASN, play an important in tumor angiogenesis." (PMID 31355161, 2019). "Since FASN was discovered, its role in tumor growth and intracellular signal transduction has been widely studied." (PMID 31850189, 2019). "As a matter of fact, tumor initiation and propagation are characterized by an altered activity of enzymes involved in lipid biosynthesis, such as fatty acid synthase (FASN) and desaturases." (PMID 30987375, 2019). "Conversely, FASN inhibition have been shown to decrease tumor growth and to drive apoptotic cell death." (PMID 30913248, 2019). "FASN overexpression confers many advantages to tumor cells such as the ability to preserve a high proliferation rate, and it also plays a key role in drug resistance acquisition." (PMID 30875891, 2019). "In many tumor types, mRNA and protein expression of Fatty Acid Synthase (FASN) are increased to fuel demands for de novo lipid synthesis to support new membrane formation and energy production." (PMID 30728898, 2019). "Similar to FASN-overexpressing cells, we did observe larger tumor mass of MAGL-overexpressing cells relative to vector-expressing cells ex vivo, which was suppressed upon FABP5 knockdown." (PMID 31831821, 2019). "Taken together, in vivo and in vitro data suggest that FASN is essential for cell transformation and tumor development." (PMID 31676791, 2019). "The Fatty Acid Synthase (FASN) protein-coding gene exhibits high expression levels in tumours, including PCa." (PMID 30872976, 2019). "In contrast to our in vivo findings, ex vivo analysis confirmed a larger tumor mass of FASN-overexpressing cells, indicating that FASN overexpression enhances tumor growth and metastasis." (PMID 31831821, 2019). "A recent study showed that FASN was expressed in 92% of tumor tissue samples coming from a cohort of 100 TNBC patients and its association with positive node status made evident its role as a possible predictive biomarker in this aggressive BC subtype." (PMID 30875891, 2019). "Intraperitoneal administration of the FASN inhibitor orlistat together with cisplatin significantly reduced tumor growth and tumor burden in these tumors." (PMID 31769430, 2019). "FASN expression is elevated in metastatic PCa and pharmacological FASN inhibition induces cellular cytotoxicity to limit tumor growth." (PMID 31831821, 2019). "Other studies have found that increased levels of Stearoyl-CoA desaturase 1 and fatty acid synthase in KIRC tissues are required for tumor growth and progression." (PMID 31727869, 2019). "In vivo, genetic deletion or pharmacologic inhibition of FASN before oncogenic activation prevents tumor development and invasive growth." (PMID 31676791, 2019). "Given the important involvement of the enzyme FASN in numerous tumor types, a number of inhibitors have been designed and/or tested in diverse cancer models: cerulenin, C75, C93, epigallocatechin gallate (EGCG), G28UCM, orlistat, GSK2194069 and GSK837149A." (PMID 30967773, 2019). "Here we have shown that the NF-κB activity can be suppressed by FASN inhibitor to enhance the tumour control when combined with radiotherapy." (PMID 31527721, 2019). "A key biosynthetic enzyme of de novo fatty acid synthesis, FASN is over-expressed in most tumors and its activity is required for the malignant biological behavior of tumor cells." (PMID 31122252, 2019).
tumor (continued). "Inhibition of lipogenesis by fatty acid synthase (FASN) inhibitors raises the possibility of limiting neoplasm development." (PMID 31242216, 2019). "In tumor cells, most fatty FAs are synthesized de novo by fatty acid synthase (FASN) to arrange the intensive bioenergetics and structural changes." (PMID 31159437, 2019). "Based on these results, FASN inhibitors show potential for tumor prevention when a clinical-grade compound becomes available." (PMID 31676791, 2019). "Fatty acid synthase (FASN) is a critical enzyme in lipogenesis, and blocking FASN inhibits tumor regrowth and metastasis after the withdrawal of sunitinib treatment." (PMID 31835465, 2019). "Inhibition of FASN by either small molecules (C75, orlistat) or small interfering RNA can efficiently suppress tumor cell growth in vitro and xenograft models." (PMID 31575907, 2019). "This scenario is connected to health conditions such as tumor progression, since altered fatty acid metabolism and enhanced activity of fatty acid synthase and desaturase enzymes were previously reported." (PMID 30987375, 2019). "In contrast, corresponding non-tumor tissues adjacent to the tumor generally express low levels of FASN protein." (PMID 31921669, 2019). "In contrast, potent FASN inhibitors developed by 3-V Biosciences demonstrate anti-tumor activity in vitro and in vivo and a favorable tolerability profile in a Phase I clinical trial in patients bearing solid tumors." (PMID 29872506, 2018). "It has been shown that M-CSF secreted from tumor cells leads to enhanced expression of FASN in macrophages, which polarize to an IL-10 expressing pro-tumoral phenotype." (PMID 29434587, 2018). "The tumor-suppressing signaling lipid ceramide is elevated upon FASN inhibition in 231MFP cells and this is consistent with our data showing increased levels of ceramide and hexaceramide in Pt 2402 and Pt 2449PT, respectively." (PMID 29872506, 2018). "Treatment of orlistat alone led to decreased cholesterol, saturated and unsaturated fatty acids in tumours together with reduced FASN expression, confirming the mechanism of drug action." (PMID 29569717, 2018). "We found that histopathological alterations in all AKT/c-Met mice with a tumor burden by 7 weeks post injection were consistently accompanied by an elevation of FASN expression, compared to the WT group." (PMID 35539339, 2018). "FASN signaling has been confirmed as a regulator of multiple signaling pathways during tumor progression, including cell-cell adhesion, migration, proliferation and chemokine transcription." (PMID 30619288, 2018). "Consistent with the study showing variability in sensitivity to TVB-3166 among 90 cell lines from different tumor types, our in vitro studies demonstrated a significant variability in responses to FASN inhibition in CRC." (PMID 29872506, 2018). "Taken together, our data suggested that FASN upregulated lipid generation in the tumor microenvironment to induce the lipid accumulation of DCs." (PMID 30619288, 2018). "FASN is a key enzyme responsible for the synthesis of fatty acids and a number of clinical reports link its expression with more aggressive tumour characteristics and worse clinical outcomes." (PMID 29331414, 2018). "In contrast to reported data from other tumor types, we noted a correlation between high expression of FASN and increased sensitivity to FASN inhibition in established CRC cell lines." (PMID 29872506, 2018). "Further, reduced tumor size was paralleled by lower FFAs levels, as well as loss of EGFR, FASN, and survivin expression, concomitant to upregulation of Bax and Bak proteins in in situ tumors." (PMID 29449326, 2018). "In particular, targeting FASN with chemical inhibitors has been proved to be effective in repressing tumor growth." (PMID 29552293, 2018). "Our data suggested that tumor-intrinsic FASN prevents the early step of T-cell priming against tumor-associated antigens." (PMID 30619288, 2018).
tumor (continued). "OvCa-derived FASN produces abundance lipid that facilitates the uptake of lipids abundant in the tumor microenvironment, including free fatty acids and the triacylglycerol-carrying lipoproteins VLDL and LDL." (PMID 30619288, 2018). "Analysis of lipid content also revealed that tumor-conditioned medium from ID8 cell with higher FASN expression had a higher level of triacylglycerol and fatty acids (data not shown)." (PMID 30619288, 2018). "Accordingly, inhibiting FASN by FASN inhibitor can partly restore the immunostimulatory activity of TIDCs and extended tumor control by evoking protective anti-tumor immune responses." (PMID 30619288, 2018). "Subsequently, Western blot images showed that FASN expression in tumors from Orlistat‐treated transgenic mice showed that tumor growth inhibition correlated with reduced FASN expression when compared to vehicle." (PMID 29449326, 2018). "To explore how FASN inhibition affects anti-tumor immune response in vivo, we analyzed tumor-infiltrating immune cells in ID8 mice treated with FASN inhibitor cerulenin, a small molecule antibiotic." (PMID 30619288, 2018). "Potent FASN inhibitors (TVBs) developed by 3-V Biosciences demonstrate anti-tumor activity in vitro and in vivo and a favorable tolerability profile in a Phase I clinical trial." (PMID 29872506, 2018). "In the context of the tumor microenvironment, FASN expression by TAMs polarized cells toward a pro-tumoral phenotype expressing IL-10." (PMID 30619850, 2018). "We uncover an unexpected role for tumor intrinsic FASN as a driver of DCs malfunction in the tumor microenvironment by lipid accumulation." (PMID 30619288, 2018). "When orlistat was combined with cisplatin (at either time point), MRS‐measured lipid levels in the tumours were increased when compared to orlistat alone despite the FASN expression remaining suppressed." (PMID 29569717, 2018). "Immunohistological analysis of patient tumor tissues showed that all cases were positive for FASN expression, with the lowest expression observed in Pt 2377PT and LM." (PMID 29872506, 2018). "We evaluated the effect of TVB-3664 on tumor growth in nine CRC patient-derived xenografts (PDXs) and investigated molecular and metabolic changes associated with CRC responsiveness to FASN inhibition." (PMID 29872506, 2018). "A potential mechanism of enhanced FASN activity with sustained tumor growth is by direct activation of cellular survival signaling pathways like Wnt/ß-catenin or oncogenic signaling pathway like PI3K/Akt." (PMID 29483509, 2018). "Consistent with increased infiltration of cytotoxic T cell populations, we also observed more IFN-r+ and Granzyme B+ functional CD8+ T cells and less Eomes+ exhausted CD8+ T cells in FASN inhibitor-treated OvCa tumor." (PMID 30619288, 2018). "We also report that Fasnall, a novel FASN inhibitor that demonstrates anti-tumor activity in vivo, is a potent and efficacious antiviral, blocking HIV-1 replication in both tissue culture and primary cell models of HIV-1 replication." (PMID 28962653, 2017). "We also report that Fasnall, a novel FASN inhibitor with anti-tumor activity potently reduces HIV-1 production with minimal effects on cellular viability." (PMID 28962653, 2017). "Biological targets of apigenin relevant to tumor potential are known to involve MAPK/NFkappaB, phospho-JAK1/ STAT3 signaling, VEGF, aromatase, proteasomal processes, fatty acid synthase and the Fas-associated protein with death domain (FADD)." (PMID 28441391, 2017). "We recently reported the discovery of a thiophenopyrimidine molecule—Fasnall—that potently and selectively inhibits FASN activity in vitro and also demonstrates anti-tumor activity in vivo." (PMID 28962653, 2017). "FASN-induced tumor progression is mediated by CD44, a transmembrane protein that promotes tumor invasion via activation of Akt signaling pathway." (PMID 29100311, 2017).